PLOD2 (procollagen-lysine,2-oxoglutarate 5-dioxygenase 2)
Diseases named in the same sentence as PLOD2 in open-access papers (continued):
Sharing a sentence is not in itself a finding about the gene and the disease.
glioblastoma (11 papers, 2017 to 2023). The most malignant astrocytic tumor (WHO grade IV). "PLOD1 and PLOD2 were shown to be involved in hypoxia-induced metastasis and glioblastoma tumor progression." (PMID 36064320, 2022). "We subsequently investigated the role of PLOD2 in migration and invasion of glioblastoma in in vitro and in vivo systems." (PMID 28423580, 2017). "In conclusion, the results indicated that PLOD2 was a gene of clinical relevance with implications in glioblastoma invasion and treatment strategies." (PMID 28423580, 2017). "In summary, we investigated the value of PLOD2 as a clinical biomarker and its functions in glioblastoma." (PMID 28423580, 2017). "Through histology-based expression profiling, PLOD2 has been identified as a novel prognostic marker in glioblastoma." (PMID 28423580, 2017). "The median PFS for glioblastoma patients with low and high PLOD2 expression was 10.22 months (95% CI, 6.03–14.41) and 7 months (95% CI, 6.141–7.859), respectively." (PMID 28423580, 2017). "Here, we examined the expression and function of PLOD2 in glioblastoma with an emphasis on its possible role in invasion." (PMID 28423580, 2017). "Eight circRNAs, including circ_COL1A2, circ_PTN, circ_VCAN, circ_SMO, circ_PLOD2, circ_GLIS3, circ_EPHB4, and circ_CLIP2 showed significantly higher expression in glioblastoma (GBM) than in normal tissues." (PMID 28969099, 2017). "Our findings indicate that overexpression of PLOD2 is induced by hypoxia and promotes invasion and migration of glioblastoma cells." (PMID 28423580, 2017). "Based on these results, we used the data from TCGA and REMBRANDT databases to determine whether PLOD2 could be used as a biomarker to distinguish between non-glioblastoma and glioblastoma patients." (PMID 28423580, 2017). "To determine whether PLOD2 was differentially expressed between glioblastoma and normal tissues, we broadly examined microarray data from patient samples within the Oncomine database." (PMID 28423580, 2017). "This study indicated that PLOD2 may represent a potential therapeutic target for the prevention of glioblastoma invasion." (PMID 28423580, 2017). "Drugs or specific inhibitors of PLOD2 may therefore block collagen fiber biogenesis and potentially improve survival rates in patients with glioblastoma." (PMID 28423580, 2017). "This study aimed to investigate the role of Procollagen-Lysine, 2-Oxoglutarate 5-Dioxygenase 2 (PLOD2) in glioblastoma (GBM) pathophysiology." (PMID 35682709, 2022). "The expression levels of circ_COL1A2, circ_PTN, circ_VCAN, circ_PLOD2, circ_SMO, circ_CLIP2, circ_GLIS3, and circ_EPHB4 in glioblastoma (GBM) are significantly higher than those in normal tissues." (PMID 30064463, 2018). "Therefore, illuminating the expression and function of PLOD2 in glioblastoma may lead to the development of additional therapeutic strategies." (PMID 28423580, 2017). "Here, we investigated the role of procollagen-lysine 2-oxoglutarate 5-dioxygenase 2 (PLOD2), an enzyme catalyzing collagen cross-linking, in the biology of glioblastoma invasion." (PMID 28423580, 2017). "PLOD2 was highly expressed in grade III astrocytomas and to a greater degree in glioblastoma, whereas staining was absent or weak and appeared in fewer cells in non-neoplastic brain tissue samples and grade II astrocytomas." (PMID 28423580, 2017).
osteosarcoma (9 papers, 2020 to 2025). A usually aggressive malignant bone-forming mesenchymal neoplasm, predominantly affecting adolescents and young adults. "Our study is the first to explain the association between PLOD2 expression and tumor stages in osteosarcoma tissue." (PMID 36632453, 2023). "Our investigations also revealed that the levels of APLN and PLOD2 expression are positively associated with tumor staging in patients with osteosarcoma." (PMID 36632453, 2023). "IHC staining with PLOD2 antibody in osteosarcoma tissue revealed significant associations with clinical disease stages." (PMID 36632453, 2023). "As reported, PLOD2 plays an important role in TIICs of osteosarcoma, such as macrophages, CD8+ T cells, DC, B cells, and Th1cells." (PMID 39068670, 2024). "In conclusion, our study demonstrates that APLN promotes PLOD2 expression and the migration of human osteosarcoma cells via the MST1, MOB1 and YAP signaling cascades and hsa_circ_0000004/ miR-1303 axis." (PMID 36632453, 2023). "Osteosarcoma is a highly mortal bone tumor, with a high metastatic potential, promoted in part by the enzyme procollagen-lysine 2-oxoglutarate 5-dioxygenase 2 (PLOD2)." (PMID 36632453, 2023). "Our results found that APLN increases the expression of PLOD2 in osteosarcoma tissue, and thereby promotes osteosarcoma cell migration and induces osteosarcoma metastasis." (PMID 36632453, 2023). "Further correlation analysis found BNIP3 to have a significantly positive correlation with MYC, NELL1, SAR1A, PLOD2, and other genes proven to promote osteosarcoma metastasis." (PMID 37190333, 2023). "The results indicate that circ_0000004 acts as a sponge of miR-1303 and thus facilitates APLN-induced osteosarcoma cell migration and increases PLOD2 expression." (PMID 36632453, 2023). "The relationship between clinicopathological features and PLOD2 expression in 22 osteosarcoma patients." (PMID 36276118, 2022). "By functional experiments we found that PLOD2 promoted osteosarcoma migration, invasion and angiogenesis in vitro." (PMID 36276118, 2022). "Furthermore, PLOD2 has been found to play a role in immune cell infiltration in osteosarcoma, suggesting its potential as a target for immunotherapy." (PMID 40906383, 2025). "Levels of APLN and PLOD2 protein correlated positively with osteosarcoma clinical stages." (PMID 36632453, 2023). "A positive correlation was found between APLN and PLOD2 expression in osteosarcoma tissue." (PMID 36632453, 2023). "Our evidence demonstrates that APLN enhances PLOD2-dependent metastatic osteosarcoma." (PMID 36632453, 2023). "Increasing level of PLOD2 in osteosarcoma tissue correlates with lymphatic and distant metastasis." (PMID 36632453, 2023). "We examined whether these five signaling pathways mediate APLN-induced increases in PLOD2 expression and promote osteosarcoma cell migration." (PMID 36632453, 2023). "Overexpression of PLOD2 facilitated osteosarcoma cell migration, invasion, and angiogenesis." (PMID 38023248, 2023). "In addition, osteosarcoma tissue revealed upregulated levels of PLOD2 mRNA expression compared to those in normal bone tissue." (PMID 36632453, 2023). "Similarly, our study shows that minoxidil suppresses APLN-induced promotion of PLOD2 expression, leading to the inhibition of osteosarcoma cell migration." (PMID 36632453, 2023). "Similarly, the GEO dataset (GSE16008) analysis indicated significantly higher PLOD2 mRNA expression in osteosarcoma tissue compared with levels in normal bone tissue." (PMID 36632453, 2023). "We conferred that the high expression of PLOD2 in osteosarcoma may repress immune cell infiltration, especially CD4 and CD8A T cells." (PMID 36276118, 2022). "Moreover, the upregulation of PLOD2 in osteosarcoma is related to lymphatic metastasis and distant metastasis." (PMID 36081989, 2022).
osteosarcoma (continued). "In addition, the baseline information of 22 osteosarcoma patients have been listed and the high expression of PLOD2 was correlated with patients’ Enneking stage and distant metastasis." (PMID 36276118, 2022). "Thus, PLOD2 is a promising molecular target for the treatment of osteosarcoma metastases." (PMID 36632453, 2023). "Similarly, levels of APLN and PLOD2 mRNA synthesis were upregulated in osteosarcoma tissue." (PMID 36632453, 2023). "We found that inhibition of YAP expression significantly reduced levels of PLOD2 expression and osteosarcoma cell migration, while transfecting osteosarcoma cells with MST1 and MOB1 siRNAs significantly reduced APLN-induced promotion of YAP binding to the PLOD2 promoter region." (PMID 36632453, 2023). "However, the functions and regulatory mechanisms of PLOD2 have not been elucidated in osteosarcoma metastasis." (PMID 36632453, 2023). "Osteosarcoma tissues expressed no significant PLOD2/3 than normal bone tissues in GSE33382." (PMID 33134376, 2020). "In our study, PLOD1 expression, not PLOD2 and PLOD3 expression, increased in osteosarcoma tissues compared with normal tissues." (PMID 33134376, 2020). "We found that PLOD1 was upregulated in osteosarcoma tissues when compared with normal bone tissues in GSE16088 and GSE33382, while the expression pattern of PLOD2 and PLOD3 was not consistent in two public datasets." (PMID 33134376, 2020). "Results of RT-PCR in 56 osteosarcoma tissues revealed that expression of PLOD1 was higher in patients with lung metastasis presented at diagnosis than those without metastasis (P < 0.01), while PLOD2 and PLOD3 expression presented no significance between two groups (all P > 0.05)." (PMID 33134376, 2020).
colorectal cancer (8 papers, 2017 to 2025). A primary or metastatic malignant neoplasm that affects the colon or rectum. "Included within the upregulated genes in the concurrent mutation group were some previously linked with colorectal cancer carcinogenesis, including NFKBIZ, CCL20, LCN2, PLOD2, MUC1, and MUC4." (PMID 40757636, 2025). "Overexpression of PLOD2 has been shown to facilitate colorectal cancer proliferation, invasion, and metastasis, both in vitro and in vivo." (PMID 40757636, 2025). "PLOD2 has been reported as an oncogenic gene in colorectal cancer and functions by stabilizing USP15, leading to AKT/mTOR-regulated progrowth signaling." (PMID 40757636, 2025). "In colorectal cancer, PLOD2 was closely related to tumor progression, grading and N stage." (PMID 34944486, 2021). "Furthermore, PLOD2 has been identified as a potential therapeutic target for colorectal cancer." (PMID 39840054, 2024). "PLOD2 and PLOD3 were among 54 glycoproteins found to be upregulated in colorectal cancer compared with normal tissue." (PMID 31446433, 2019).
liver cancer (8 papers, 2020 to 2024). An epithelial or non-epithelial malignant neoplasm that arises from the liver. "According to the literatures, PLOD2 can be observed in cancer-associated fibroblasts in melanoma, lung adenocarcinoma, and liver cancer." (PMID 34944486, 2021). "Glucosamine-6-phosphate deaminase 1 (GNPDA1) and procollagen-lysine (PLOD2) are upregulated in liver cancer and promote tumor proliferation and migration, which are correlated with poor prognosis." (PMID 34557495, 2021). "We verified the expression levels of the representative gene pair PLOD2 /CDKN1B in 45 liver cancer samples, and combined with the OS and RFS of the corresponding patients, we found that PLOD2 /CDKN1B can better predict the prognosis of the patients." (PMID 34095224, 2021). "At the protein level, we found that the expression of PLOD2 in liver cancer cell lines was higher than in normal liver cells, and it was also higher in non-invasive liver cancer cells." (PMID 34095224, 2021). "And PLOD2 is highly expressed in tumor tissues compared to normal tissues, including liver cancer." (PMID 39308686, 2024). "According to the ONCOMINE data, the hepatic expression levels of PLOD2 and PLOD3 were remarkably elevated in liver cancer tissue compared to normal liver tissue." (PMID 33014843, 2020).
biliary tract cancer (7 papers, 2018 to 2025). "PLOD2 is induced by hypoxia and affects chemotherapy resistance in biliary tract cancer patients through EMT." (PMID 38044951, 2023). "For example, in biliary tract cancer, hypoxia has been show to promote the expression of procollagen-lysine 2-oxoglutarate 5-dioxygenase 2 (PLOD2), a collagen modifying enzyme, which can promote EMT and resistance to gemcitabine." (PMID 30487436, 2018). "Previous studies have exhibited that PLOD2 was high-expressed in various types of cancer including HCC, OSCC and biliary tract cancer (9, 29; B. 10)." (PMID 36276118, 2022). "The hypoxia-induced gene, procollagen-lysine 2-oxoglutarate 5-dioxygenase 2 (PLOD2), was induced by hypoxia conditions in biliary tract cancer cell and influence gemcitabine resistance through EMT." (PMID 34003341, 2021).
esophageal squamous cell carcinoma (7 papers, 2018 to 2022). Esophageal squamous cell carcinoma (ESCC) is a type of esophageal carcinoma (EC) that can affect any part of the esophagus, but is usually located in the upper or middle third. "For example, the high expression of PLOD1 and PLOD2 observed in esophageal squamous-cell carcinoma is negatively associated with expression of tumor suppressor gene." (PMID 31446433, 2019). "PLOD2, highly expressed in esophageal squamous cell carcinoma, promotes the invasion and metastasis of esophageal squamous cell carcinoma through the epithelial to mesenchymal transition via the FAK/AKT signal pathway." (PMID 36081989, 2022). "For example, in esophageal squamous cell carcinoma, the high expression of PLOD2 was closely related to tumor size and intrahepatic metastasis." (PMID 34944486, 2021). "In esophageal squamous cell carcinoma, the expression of tumor suppressor gene esophageal cancer-related gene 4 was negatively correlated with PLOD1 and PLOD2." (PMID 33420370, 2021). "In esophageal squamous-cell carcinoma (ESCC), expression of the tumor suppressor gene esophageal cancer-related gene 4 has a negative association with PLOD1 and PLOD2." (PMID 30003082, 2018).
lung adenocarcinoma (6 papers, 2014 to 2024). A carcinoma that arises from the lung and is characterized by the presence of malignant glandular epithelial cells. "Other studies also reported on the possible role of the LH2/PLOD2 Glc-T activity in lung adenocarcinoma progression." (PMID 37446392, 2023). "Although PLOD2 was confirmed to be related to poor prognosis in lung adenocarcinoma, the regulatory mechanism and function of PLOD2 in human lung adenocarcinoma is poorly understood." (PMID 29072684, 2017). "Although PLOD2 is believed to negatively correlate to poor prognosis in murine lung adenocarcinoma, the regulation mechanism and function of PLOD2 in human lung adenocarcinoma is poorly understood." (PMID 29072684, 2017). "In a murine lung adenocarcinoma model, CAF‐expressed PLOD2‐mediated collagen cross‐linking increased tumour invasiveness." (PMID 39164826, 2024). "Further analysis showed that PLOD2 was an adverse prognosis marker in lung adenocarcinoma patients at stage I but not at stage III and was independent of smoking history and gender." (PMID 29072684, 2017).
renal carcinoma (6 papers, 2019 to 2023). A carcinoma arising from the epithelium of the renal parenchyma or the renal pelvis. "Moreover, three core glycolytic risk genes, CD44, PLOD1 and PLOD2, were capable of promoting the proliferation and invasion of renal cancer cells." (PMID 33287763, 2020). "To investigate the practical application of PLOD2 inhibitors, we investigate the role of the novel PLOD2 inhibitor, Minoxidil, in the occurrence and progression of renal cancer." (PMID 38008826, 2023). "Then we wanted to clarify the effect of PLOD2 in the development of renal cancer and its molecular mechanism of m6A methylation modification." (PMID 34179084, 2021). "MTT and Transwell assays revealed that silencing of CD44, PLOD1 and PLOD2 suppressed the proliferation and invasion of renal cancer cells." (PMID 33287763, 2020). "MiRNA-29a targets heat shock protein 47 in cervical SCC, and miR-26a/b affects lysyl oxidase-like (LOXL) 2 and procollagen-lysine, 2-oxoglutarate 5-dioxygenase 2 (PLOD2) levels in renal cancer cells." (PMID 31521169, 2019). "At the cell level, the effects of PLOD2 m6A modification on the proliferation, migration, invasion and apoptosis of renal carcinoma cells were analyzed to explore its molecular mechanism in the occurrence and development of renal carcinoma." (PMID 34179084, 2021). "Therefore, we validated the biofunctions of CD44, PLOD1 and PLOD2 in renal cancer cells through further vitro experiments." (PMID 33287763, 2020). "In our study, we observed a significant positive correlation between PLOD2 and HIF1A in renal cancer tissues, with HIF1A promoting the expression of PLOD2." (PMID 38008826, 2023). "NNMT, PLOD2, HAPLN3, PLIN2, and SLC16A3 showed medium to strong tumor-specific staining in more than 90% renal cancer samples, indicating higher general applicability of these biomarkers." (PMID 35440542, 2022). "For example, the glycolysis process was found to be remarkably upregulated in RCC samples, and its core regulatory genes PLOD1, PLOD2, and CD44 could promote the proliferation of renal cancer cells." (PMID 35784919, 2022).
clear cell renal cell carcinoma (5 papers, 2021 to 2026). "To investigate the role of PLOD2 in the proliferation of clear cell renal cell carcinoma (ccRCC), we knocked down PLOD2 in 786-O and Caki-1 cells." (PMID 41584042, 2026). "Among them, the modification and expression level of m6A on PLOD2 mRNA were significantly increased in renal clear cell carcinoma tissues, which aroused our research interest." (PMID 34179084, 2021).
endometrial carcinoma (5 papers, 2015 to 2025). A malignant tumor arising from the epithelium that lines the cavity of the uterine body. "The expression of procollagen-lysine, 2-oxoglutarate, 5-dioxygenase 2 (PLOD2) is upregulated in endometrial cancer cells under hypoxic conditions." (PMID 40746599, 2025). "In endometrial carcinoma cells, PLOD2 modulated cell migration, invasion, and EMT via PI3K/Akt signaling under hypoxic conditions." (PMID 34944486, 2021). "The PLOD2 gene has also been found to be a good marker for differentiating endometrial cancer from normal endometrium and atypical hyperplastic endometrium." (PMID 26033187, 2015).
lymph node metastasis (5 papers, 2015 to 2023). "Patients with highly expressed PLOD2 in TCs (PLOD2TCs) and FLCs (PLOD2FLCs) showed poor differentiation, a worse pattern of invasion (WPOI) and more lymph node metastasis (LNM), contributing to higher postoperative metastasis risk and poor survival time." (PMID 34944486, 2021). "Similarly, our research showed that OSCC patients with higher PLOD2 in FLCs had worse tumor differentiation and WPOI and higher risk of lymph node metastasis compared with lower PLOD2FLCs." (PMID 34944486, 2021). "However, upregulated PLOD2 in FLCs (PLOD2FLCs) were positively correlated with worse tumor differentiation (p < 0.001), worst pattern of invasion (WPOI) (p < 0.001) and high risk of lymph node metastasis (LNM) (p < 0.001)." (PMID 34944486, 2021). "In addition, the expression of PLOD2 was significantly higher in patients with lymph node metastasis as compared to those without lymph node metastasis and increased with increasing tumor stage." (PMID 38008826, 2023).
non-small cell lung carcinoma (5 papers, 2018 to 2023). A group of at least three distinct histological types of lung cancer, including non-small cell squamous cell carcinoma, adenocarcinoma, and large cell carcinoma. "In addition, FOXA1 transcription factor has been identified as a potential regulator of PLOD2 expression during the progression of non-small cell lung cancer." (PMID 33014843, 2020). "Interestingly, two target genes identified in a previously conducted microarray study to be up-regulated by RASSF1C in breast and non-small cell lung cancer (NSCLC) cells are prolyl 4-hydroxylase alpha-2 (P4HA2) and procollagen-lysine, 2-oxoglutarate 5-dioxygenase 2 (PLOD2)." (PMID 36826019, 2023).
osteogenesis imperfecta (5 papers, 2020 to 2023). Osteogenesis imperfecta (OI) comprises a heterogeneous group of genetic disorders characterized by increased bone fragility, low bone mass, and susceptibility to bone fractures with variable severity. "Thecause of osteogenesis imperfecta of the X and XI types isa violation of the processing and cross-linking of collagendue to mutations in the SERPINH1 and FKBP10 genes, respectively.Mutations in the PLOD2 and BMP1 genes lead toincomplete type XII osteogenesis." (PMID 33659802, 2020).